TMEM106B (transmembrane protein 106B)
Diseases named in the same sentence as TMEM106B in open-access papers (continued):
Sharing a sentence is not in itself a finding about the gene and the disease.
lung adenocarcinoma (2 papers, 2018 to 2025). A carcinoma that arises from the lung and is characterized by the presence of malignant glandular epithelial cells. "According to this TCGA lung adenocarcinoma data set, containing 517 samples, 19% of the samples (n = 98) show either gene amplification or upregulation of the mRNA expression for TMEM106B." (PMID 30013069, 2018). "Next, we wanted to assess the clinical relevance of these findings so as to determine the status of TMEM106B expression in human lung adenocarcinoma data sets and whether its expression profile could be associated as a prognostic indicator of disease outcome." (PMID 30013069, 2018). "The data therefore suggest that TMEM106B could potentially be utilized as a prognostic marker and indicator of poor disease outcome and importantly to be developed for intervention strategies to target lung adenocarcinoma growth and metastasis." (PMID 30013069, 2018).
anxiety disorder (1 paper, 2021). A category of psychiatric disorders which are characterized by anxious feelings or fear often accompanied by physical symptoms associated with anxiety. "In previous GWASs, SNPs in TMEM106B have been associated with MDD (e.g. the intronic SNP rs10950398), anxiety disorders (2 kb upstream variant rs3807866) and other traits." (PMID 34158615, 2021).
Ataxia (1 paper, 2020). Ataxia refers to impaired coordination of voluntary muscle movement. "No obvious hindlimb weakness or ataxia phenotypes were observed in 5‐month‐old and 16‐month‐old Tmem106b+/−Grn−/− and Tmem106b−/−Grn+/− mice (our unpublished observations), suggesting that total loss of both PGRN and TMEM106B is required for the development of these behavioral phenotypes." (PMID 32852886, 2020).
atherosclerosis (1 paper, 2025). A disease characterized by the build-up of fatty material and calcium deposition in the arterial wall resulting in partial or complete occlusion of the arterial lumen. "We previously reported that ANRIL regulated endothelial cell functions associated with atherosclerosis by upregulating multiple genes, including TMEM106B." (PMID 40383150, 2025). "Consistent with our finding of the causal role of ANRIL in atherosclerosis, genetic variants of TMEM106B significantly increased the risk of CAD and interacted with ANRIL variants to confer an epistatic effect on risk of CAD." (PMID 40383150, 2025).
Brain atrophy (1 paper, 2020). Partial or complete wasting (loss) of brain tissue that was once present. "Besides the association with TMEM106B in Subtype B, protective variants near MTUS2 were identified which are in close vicinity to HMGB1, a locus that has been previously implicated in brain atrophy." (PMID 32492070, 2020).
colon cancer (1 paper, 2021). "As for MAGI2-AS3, it has been found to promote the progression of colon cancer by regulating the miR-3163/TMEM106B axis." (PMID 33836755, 2021). "Actually, MAGI2-AS3 is found to promote colon cancer progression by regulating the miR-3163/TMEM106B axis." (PMID 33836755, 2021).
endometriosis (1 paper, 2019). The growth of functional endometrial tissue in anatomic sites outside the uterine body. "TMEM106B was found upregulated in ectopic versus eutopic endometrium of women with endometriosis." (PMID 31552087, 2019).
epilepsy (1 paper, 2023). A brain disorder characterized by episodes of abnormally increased neuronal discharge resulting in transient episodes of sensory or motor neurological dysfunction, or psychic dysfunction. "TMEM106B was a top protein candidate that was elevated in AD when compared to the epilepsy group." (PMID 37521285, 2023). "Validation of the LFQ-MS findings in five cases per group with the semiquantification of immunohistochemistry similarly showed the same trends for TMEM106B, with a 3.9-fold increase in AD vs. epilepsy (p = 0.095) and a 5.0-fold increase in AD vs. control (p = 0.095)." (PMID 37521285, 2023). "TMEM106B (Q9NUM4) was among the top 20 most significantly altered proteins when comparing AD vs. epilepsy with the highest fold change at an 18.9-fold increase (p = 3.22 x 10−6) and was a top protein candidate for validation with cell and regional localization." (PMID 37521285, 2023).
experimental autoimmune encephalomyelitis (1 paper, 2023). An autoimmune demyelinating disease of the central nervous system that is produced experimentally in animals by the injection of homogenized brain or spinal cord in Freund's adjuvant. "Relative to wild-type mice, hypomorphic mice with a reduction in TMEM106B have increased axonal damage and lipid droplet accumulation in the spinal cord following myelin-oligodendrocyte-glycoprotein-induced experimental autoimmune encephalomyelitis." (PMID 37443768, 2023). "The increased insoluble TMEM106B led us to examine the consequence of reducing TMEM106B in the inflammatory model of experimental autoimmune encephalomyelitis (EAE), and the cuprizone model, to determine if decreased TMEM106B in a hypomorphic mouse impacts the clearance of lipids." (PMID 37443768, 2023).
glioma (1 paper, 2025). A benign or malignant brain and spinal cord tumor that arises from glial cells (astrocytes, oligodendrocytes, ependymal cells). "To comprehensively evaluate TMEM106A's role in glioma, we began by examining all its relatives from the entire TMEM106 family (including TMEM106A, TMEM106B, and TMEM106C) within the context of glioma." (PMID 41354084, 2025).
hypomyelinating leukodystrophy 16 (1 paper, 2024). "A missense mutation, p.Asp252Asn, of TMEM106B is associated with hypomyelinating leukodystrophy 16 (HLD16), which is an oligodendroglial cell-related white matter disorder causing thin myelin sheaths or myelin deficiency in the central nervous system (CNS)." (PMID 39194695, 2024).
Lysosomal disease (1 paper, 2023). "However, TMEM106B has opposing effects in different mouse models of lysosomal diseases." (PMID 37443768, 2023).
microcephaly (1 paper, 2021). A congenital or acquired developmental disorder in which the circumference of the head is smaller than normal for the person's age and sex. "In the present case microcephaly is most likley due to reduction in the size of the brain parenchyma, primarily reduction of gray matter; thus, it is questionable to what extend monosomy of TMEM106B contributes to observed phenotype." (PMID 33613193, 2021).
neuroblastoma (1 paper, 2014). Neuroblastoma (NB) is the most common solid, extracranial childhood tumor. "We found that overexpression of either TMEM106B or PGRN transgene in SK-N-SH neuroblastoma cells does not immediately affect endogenous levels of PGRN or TMEM106B mRNA, excluding the direct interaction between both in transcription regulation of mutual genes." (PMID 24684749, 2014).
Neurodegeneration (1 paper, 2025). Progressive loss of neural cells and tissue. "The mutation of the TMEM106B gene on Chromosome 7, a homolog of TMEM106C, is a risk factor of neurodegeneration disease." (PMID 41153414, 2025).
secondary progressive multiple sclerosis (1 paper, 2023). A multiple sclerosis with a clinical course characterized by a progressive accumulation of neurological disability, independent of relapses, following an initial relapsing-remitting (RR) phase. "Plaques from an individual with secondary progressive multiple sclerosis (SPMS) also showed TMEM106B+ puncta." (PMID 37443768, 2023).
neurodegenerative disease (45 papers, 2013 to 2026). A disorder of the central nervous system characterized by gradual and progressive loss of neural tissue and neurologic function. "Advances in preclinical disease models as well as therapeutic targeting of PGRN- and TMEM106B-associated neurodegenerative diseases are reviewed." (PMID 40713630, 2025). "Genetic variation in TMEM106B is known to influence healthy aging and modify the risk and disease presentation of several neurodegenerative diseases." (PMID 40269985, 2025). "Mutations and single nucleotide polymorphisms (SNPs) of the TMEM106B gene lead to lysosomal deficits in the clearance of misfolded proteins, which are the main pathological changes in multiple Neurodegenerative diseases." (PMID 38710967, 2024). "The TMEM106B gene mutations lead to lysosomal dysfunction and accelerate the pathological progression of Neurodegenerative diseases." (PMID 38710967, 2024). "Over the past decade SNPs in TMEM106B have emerged as a reproducible genetic risk factor for development and severity of neurodegenerative diseases, especially FTLD-TDP." (PMID 38915598, 2024). "SNPs in the human TMEM106B gene confer risk of development and severity for a number of neurodegenerative diseases, but most significantly in cases of FTLD-TDP caused by PGRN haplo-insufficiency." (PMID 38915598, 2024). "In this review, we will introduce current knowledge of TMEM106B in physiological and pathological function and its potential association with Neurodegenerative diseases." (PMID 38710967, 2024). "Taken together, these results further suggest an important role of TMEM106B in neurodegenerative diseases and provide new insights into the cellular processes associated with the aberrant TMEM106B pathology in both murine models and human diseases." (PMID 39606446, 2024). "Six SNPs of TMEM106B were found to modify the disease risk for several Neurodegenerative diseases and are associated with their clinical and pathological phenotypes." (PMID 38710967, 2024). "Transmembrane protein 106B (TMEM106B) is a genetic risk variant for many neurodegenerative diseases." (PMID 37545650, 2023). "Together, these studies link the elevated levels of TMEM106B with higher risk for developing neurodegenerative diseases." (PMID 37563705, 2023). "Prior genetics studies revealed a robust relationship between several SNPs in the TMEM106B gene and the risk for developing neurodegenerative diseases." (PMID 37563705, 2023). "In light of this new possibility, a re-evaluation of previous opinion of TMEM106B’s function and association with neurodegenerative diseases is needed." (PMID 37563705, 2023). "Alterations in TMEM106B function have been linked to neurodegenerative disease, and defects in dendritic trafficking of lysosomes and axons." (PMID 37443768, 2023). "One of the major neurodegenerative diseases associated with TMEM106B is frontotemporal dementia (FTD)." (PMID 37563705, 2023). "Together, these studies of genetics showed that TMEM106B variants are associated with the onset or clinical manifestation of major neurodegenerative diseases, highlighting the importance of the interaction with TDP-43 in the brain." (PMID 37563705, 2023). "Ren and colleagues conducted a stratification analysis and highlighted more pronounced effects of TMEM106B rs3173615 variant on the transcriptome in neurodegenerative diseases than in healthy controls." (PMID 33461566, 2021). "TMEM106B is a known modifier of neurodegenerative disease and cognitive aging, which has been previously linked with cognitive performance." (PMID 32492070, 2020). "Third, the effect of PGRN on TMEM106B turnover and proper lysosomal function is much more evident in the aged brain, consistent with notions that aging is the biggest risk factor for neurodegenerative diseases and lysosomal function declines with age." (PMID 28126008, 2017).
neurodegenerative disease (continued). "This study provides a better understanding of pathogenic functions of TMEM106B, which is a risk factor for the progression of neurodegenerative diseases that are associated with endosomal defects in the aged brain." (PMID 26651479, 2015). "The findings of the present study contribute to a better understanding of the role of TMEM106B in the cellular pathogenesis of neurodegenerative diseases that are associated with the endolysosomal and autophagy pathway and as a risk factor for these diseases." (PMID 26651479, 2015). "Interestingly, there was also downregulation of non-coding RNA 1700016P03Rik, encoding miR132 and miR212, which downregulates TMEM106B and which has consistently been downregulated in neurodegenerative diseases." (PMID 40269985, 2025). "Thus, it is possible that the AluYb8 insertion in the risk haplotype causes an increase in TMEM106B protein levels to affect the development and presentation of neurodegenerative diseases." (PMID 40713630, 2025). "The precise mechanism by which GRN and TMEM106B variants affect brain aging and whether the relevant pathways also contribute to an increased risk for neurodegenerative diseases are currently unclear." (PMID 40713630, 2025). "In addition to being a disease modifier for FTD, several genome-wide association studies (GWAS) have uncovered TMEM106B variants that are relevant to other neurodegenerative diseases." (PMID 39606446, 2024). "Finally, we discussed the potential pathogenic role of TMEM106B fibrils and the future directions for TMEM106B research in Neurodegenerative diseases." (PMID 38710967, 2024). "It is still unclear whether the TMEM106B aggregates that have been described in neurodegenerative disease and normal aging are a cause or consequence of cellular injury or death." (PMID 39606446, 2024). "Additionally, TMEM106B is implicated in the pathology of various other neurodegenerative diseases (NDs), extending beyond FTLD." (PMID 39872397, 2024). "TMEM106B has also been implicated in neurodegenerative diseases other than ALS/FTLD-TDP." (PMID 38886865, 2024). "We also included TMEM106B gene mutations that cause neurodegenerative diseases." (PMID 38710967, 2024). "The findings that higher levels of TMEM106B are associated with higher risk for developing neurodegenerative diseases suggests that the overexpression of TMEM106B might be a plausible model to study its involvement in the pathogenesis process." (PMID 37563705, 2023). "Mutations of the gene TMEM106B are risk factors for diverse neurodegenerative diseases." (PMID 37563705, 2023). "TMEM106B polymorphisms have been associated with brain aging and many neurodegenerative diseases." (PMID 37146150, 2023). "Interestingly, TMEM106B dysfunction is also implicated in neurodegenerative diseases in elderly patients." (PMID 36003149, 2022). "However, GRN and TMEM106B have also been linked to brain health and many other neurodegenerative diseases." (PMID 35379992, 2022). "Besides FTLD, GRN and TMEM106B have been implicated in brain aging and many other neurodegenerative diseases." (PMID 32852886, 2020). "To determine whether TMEM106B risk alters the association between microglia and select cytokines previously found to be involved in neurodegenerative disease, we performed multiple linear regressions adjusting for age at death in those without and with the risk genotype." (PMID 41264095, 2025). "Importantly, it remains unclear how the TMEM106B haplotype modifies a disease risk across various neurodegenerative diseases as well as brain aging." (PMID 40713630, 2025). "Recent studies identified that the C-terminal fragment (CTF) (AA120 - 254) of TMEM106B can form amyloid filaments in the brain of patients with a variety of neurodegenerative diseases as well as older neurologically normal individuals." (PMID 40269985, 2025).
neurodegenerative disease (continued). "Loss of TMEM106B exacerbates tau pathology, axonal damage, lipid droplet accumulation, and neurodegeneration in mouse models, suggesting TMEM106B has a protective role in neurodegenerative diseases." (PMID 40219815, 2025). "In this review, we provide an overview of PGRN and TMEM106B in neurodegenerative diseases and the endolysosomal system." (PMID 40713630, 2025). "Beyond FTLD-GRN, TMEM106B variation has also been linked to FTLD-TDP with C9orf72 repeat expansions and many other neurodegenerative diseases including AD, chronic traumatic encephalopathy, and LATE-NC." (PMID 40713630, 2025). "This review summarizes recent advances in progranulin and TMEM106B function within the endolysosomal system and neurodegenerative diseases." (PMID 40713630, 2025). "Genetic variation in Transmembrane protein 106B (TMEM106B) is known to influence the risk and presentation in several neurodegenerative diseases and modifies healthy aging." (PMID 40269985, 2025). "Recently, the C-terminal fragment of TMEM106B was demonstrated to form amyloid fibrils in the brains of patients across a diverse range of neurodegenerative diseases including AD and many ADRDs." (PMID 38915598, 2024). "While the relative toxicity of the accumulating TMEM106B CT aggregates remains uncertain, the presence of TMEM106B amyloid across a variety of neurodegenerative diseases indicates involvement in multi-proteinopathy driven neurodegeneration." (PMID 38915598, 2024). "Specifically, the molecular role TMEM106B plays in neurodegenerative disease requires further investigation." (PMID 38915598, 2024). "Recently, different research teams discovered that TMEM106B is an amyloid protein and the C-terminal domain of TMEM106B forms amyloid fibrils in various Neurodegenerative diseases and normally elderly individuals." (PMID 38710967, 2024). "Recently, studies revealed that the luminal domain of TMEM106B forms amyloid fibrils in various Neurodegenerative diseases and neurologically normal older adults." (PMID 38710967, 2024). "TMEM106B fibrils are deposited in many brain regions of patients of various Neurodegenerative diseases, but the mechanism by which TMEM106B fibrils contributes to neurodegenerative pathology is currently unclear." (PMID 38710967, 2024). "As an integral lysosomal transmembrane protein, transmembrane protein 106B (TMEM106B) regulates several aspects of lysosomal function and is associated with neurodegenerative diseases." (PMID 38710967, 2024). "In the past two years, several research groups have reported that TMEM106B forms amyloid fibrils in the brain tissue of different neurodegenerative diseases and elderly normal subjects through cryo-EM." (PMID 38710967, 2024). "The deposition of TMEM106B fibrils identified by Cryo-EM will undoubtedly highlight the role of TMEM106B in neurodegenerative diseases, but there are many questions to be answered." (PMID 38710967, 2024). "Filaments made of residues 120-254 of transmembrane protein 106B (TMEM106B) form in an age-dependent manner and can be extracted from the brains of neurologically normal individuals and those of subjects with a variety of neurodegenerative diseases." (PMID 38886865, 2024). "Significantly, the burden of TMEM106B fibrillization is much higher in most individuals with Neurodegenerative diseases, when compared with age-matched healthy controls." (PMID 38710967, 2024). "The associations of TMEM106B SNPs with the APOE gene expression and several neurodegenerative diseases also point in that direction." (PMID 38674351, 2024). "TMEM106B is a lysosomal/late endosome protein that is a potent genetic modifier of multiple neurodegenerative diseases as well as general aging." (PMID 39606446, 2024). "In the context of neurodegenerative diseases, TMEM106B has been studied in vivo using animal models of neurodegeneration, but these studies rely on overexpression or knockdown approaches." (PMID 39606446, 2024).